CDCA2 (cell division cycle associated 2)
Description:
Regulator of chromosome structure during mitosis required for condensin-depleted chromosomes to retain their compact architecture through anaphase. Acts by mediating the recruitment of phosphatase PP1-gamma subunit (PPP1CC) to chromatin at anaphase and into the following interphase. At anaphase onset, its association with chromatin targets a pool of PPP1CC to dephosphorylate substrates.
Synonyms: Repo-Man; PPP1R81
Tractability: PROTAC: UniProt records ubiquitination sites on it; ubiquitination databases record sites on it.
Gene: Protein-coding gene on chromosome 8 (25,459,199 to 25,507,911, forward strand). Ensembl gene ENSG00000184661.
Subcellular location: Nucleus
Subcellular location (Human Protein Atlas): Nucleoplasm; Cytosol
Gene Ontology:
Molecular function: protein phosphatase regulator activity; molecular condensate scaffold activity
Biological process: chromosome segregation; meiotic cell cycle; regulation of mitotic nuclear division
Cellular component: chromosome; nucleoplasm; condensed chromosome; nucleus
Genetic constraint (gnomAD): Loss-of-function variants: 31 observed, 49.8 expected, observed/expected ratio (o/e) 0.62, 90% interval 0.47 to 0.84. The upper end of that interval is the gene's LOEUF score, 0.84, which puts it in group 3 of 6, group 1 being the genes least tolerant of losing a copy. Missense variants: 1,113 observed, 1,126.3 expected, observed/expected ratio (o/e) 0.99, 90% interval 0.94 to 1.04. Synonymous variants: 407 observed, 394.28 expected, observed/expected ratio (o/e) 1.03, 90% interval 0.95 to 1.12.
Homologues: Orthologues: chimpanzee CDCA2 (94% identical), macaque CDCA2 (93% identical), rabbit CDCA2 (67% identical), dog CDCA2 (64% identical), pig CDCA2 (64% identical), guinea pig CDCA2 (55% identical), rat Cdca2 (51% identical), mouse Cdca2 (50% identical), zebrafish si:ch211-244o22.2 (18% identical). Paralogues in human: MKI67 (15% identical).
Diseases named in the same sentence as CDCA2 in open-access papers:
CDCA2 is named in the same sentence as 43 diseases in open-access papers, as found by Europe PMC text mining. Sharing a sentence is not in itself a finding about the gene and the disease. The quoted sentences say what the papers report.
melanoma (9 papers, 2007 to 2024). A malignant, usually aggressive tumor composed of atypical, neoplastic melanocytes. "CDCA2 was also reported to be a metastatic biomarker of synovial sarcoma and to promote the migration of melanoma cells." (PMID 35694386, 2022). "CDCA2 was also found to exacerbate the malignant progression of melanoma by upregulating the proliferation and migration capacity of the tumor cells." (PMID 34660326, 2021). "CDCA2 is frequently over-expressed in many tumor cells, as neuroblastoma, melanoma, breast cancer and in oral squamous cell carcinoma." (PMID 24905922, 2014). "Although, the CDCA2 gene is overexpressed in aggressive neuroblastoma tumors and melanoma cell lines, the expression status and function of CDCA2 in OSCCs are not fully characterized." (PMID 23418564, 2013). "In addition, high expression of CDCA2 has been reported in melanoma, clear cell renal cell carcinoma, and prostate cancer, and its upregulation was positively correlated with tumor progression." (PMID 34660326, 2021). "In addition to previous studies that reported CDCA2 up-regulation in aggressive neuroblastoma, melanoma, and breast cancer, we found significant up-regulation of CDCA2 in the OSCC cell lines compared with that in the HNOKs." (PMID 23418564, 2013). "High CDCA2 expression was associated with more advanced pathological features in clear-cell renal cell carcinoma (ccRCC), colorectal cancer (CRC), prostate cancer, oral squamous cell carcinoma (OSCC), lung adenocarcinoma, breast cancer, melanoma, and pancreatic ductal adenocarcinoma." (PMID 35694386, 2022). "CDCA2 can act on SMAD-specific E3 ubiquitin protein ligase 1 and inhibit the degradation of ubiquitin-dependent Aurora kinase A (AURKA) to promote melanoma progression." (PMID 39247594, 2024).
glioma (8 papers, 2020 to 2024). A benign or malignant brain and spinal cord tumor that arises from glial cells (astrocytes, oligodendrocytes, ependymal cells). "A pan-cancer analysis showed that high CDCA2 expression was associated with poor prognosis in low-grade gliomas." (PMID 39830513, 2024). "Additionally, expression of IRAG1 was negatively associated with high expression of the cell division cycle-associated protein 2 (CDCA2) in glioma." (PMID 37372987, 2023). "The regulation of CDCA2 under the hypoxia pathway was further supported by other microarray GEO datasets, which were tested in PCa, lung cancer, glioma, and breast cancer." (PMID 32509575, 2020). "Echinomycin, which blocks the binding of HIF-1α, repressed CDCA2 expression in glioma U251 cells (GSE7835)." (PMID 32509575, 2020). "Our study uses bioinformatics to analyze the important functions of CDCA2/3/4/5/7/8 in gliomas and provides insight that may help to guide clinical diagnosis and treatment." (PMID 38181024, 2024). "Further analysis identified CDCA2, 5 and 8 as independent prognostic factors for glioma." (PMID 38181024, 2024). "Wherein, NCAPG could be positively related to CDCA2 (cell division cycle-associated protein 2) in glioma, and the over-expression of NCAPG may regulate the cell cycle and promote the proliferation, migration, and invasion of glioma cells." (PMID 35992200, 2022). "Combined with the GDSC drug database, CDCA2, CDCA4, CDCA5, CDCA7, and CDCA8 have potential as clinical drug treatments for glioma." (PMID 38181024, 2024). "And subsequent multivariate COX regression analyses suggested that CDCA2, CDCA5, and CDCA8 were independent prognostic factors for glioma." (PMID 38181024, 2024). "CDCA2, CDCA4, CDCA5, CDCA7, and CDCA8 showed high accuracy for diagnosing gliomas, with CDCA7 having the highest accuracy (AUC: 0.982)." (PMID 38181024, 2024). "Glioma data from TCGA, the China Glioma Genome Atlas Project (CGGA) and the gene expression omnibus (GEO) database all demonstrated that CDCA2, 3, 4, 5, 7 and 8 are prognostic markers for glioma." (PMID 38181024, 2024). "CDCA2, CDCA3, CDCA4, CDCA5, CDCA7, and CDCA8 were significantly highly expressed in glioma samples." (PMID 38181024, 2024).
lung adenocarcinoma (8 papers, 2017 to 2025). A carcinoma that arises from the lung and is characterized by the presence of malignant glandular epithelial cells. "Cell division cycle associated 2 (CDCA2), upregulated in lung adenocarcinoma and oral squamous cell carcinoma, may be related to some malignant diseases." (PMID 31196027, 2019). "What is more, higher CDCA2 expression was correlated to patients' survival in some cancer types, such as in lung adenocarcinoma (LAUD), Kidney renal papillary carcinoma (KIRP), and (liver hepatocellular carcinoma) LIHC." (PMID 32509575, 2020). "Furthermore, a study on lung adenocarcinoma suggests that CDCA2 proliferates lung adenocarcinoma cells and predicts the poor prognosis for these patients." (PMID 32104702, 2020). "Previous studies had revealed that CDCA2 might be an oncogene in some cancers, such as luminal breast cancer 17, lung adenocarcinoma 18 and pancreatic ductal adenocarcinoma." (PMID 32913466, 2020). "An increasing number of reports have shown that CDCA2, which is upregulated in neuroblastoma, oral squamous cell carcinoma tissue, and lung adenocarcinoma, may be related to certain malignant diseases." (PMID 31196027, 2019). "However, the biological and clinical significance of CDCA2 in lung adenocarcinoma(LAC) has never been investigated." (PMID 28423619, 2017). "In lung adenocarcinoma cells, the expression of CCNE1, but not CCND1, was positively correlated with the CDCA2 levels." (PMID 35694386, 2022).
oral squamous cell carcinoma (8 papers, 2013 to 2022). "Previous studies also suggested that CDCA2 was overexpressed in neuroblastoma, lung cancer, and oral squamous cell carcinoma, but few reports are related to CDCA2 function in PCa." (PMID 32509575, 2020). "Cell division cycle associated 2(CDCA2) is overexpressed in neuroblastoma and oral squamous cell carcinoma, and its overexpression positively correlates to tumor progression." (PMID 28423619, 2017). "Though CDCA2 is overexpressed in aggressive neuroblastoma and oral squamous cell carcinoma, the expression profile and biological function of CDCA2 in NSCLC still remain unknown." (PMID 28423619, 2017). "Besides, CDCA2 high expression may be closely related to oral squamous cell carcinoma, a types of head and neck squamous cell carcinoma (OSCC) development by blocking cell cycle arrest and apoptosis." (PMID 36588796, 2022). "However, the relevance of CDCA2 to human malignancy including oral squamous cell carcinoma (OSCC) is unknown." (PMID 23418564, 2013). "Overexpression of CDCA2 and CDCA3 is a frequent event for oral squamous cell carcinomas (OSCC)." (PMID 32509575, 2020). "Additionally, CDCA2 overexpression promotes the proliferation of CRC cells and oral squamous cell carcinoma (OSCC) cells." (PMID 32104702, 2020).
breast carcinoma (7 papers, 2013 to 2021). "Previous studies have shown that CDCA2 is upregulated and associated with poor prognosis in some tumors, such as lung cancer, breast cancer, and pancreatic cancer." (PMID 35372372, 2021). "Knockdown of HIF-1α caused CDCA2 mRNA levels to decline in breast cancer MCF7 cells (GSE3188)." (PMID 32509575, 2020). "The overexpression of CDCA2 in breast cancer tissue was highly correlated with a poor prognosis for breast cancer patients, with an HR of 1.36." (PMID 29467944, 2018). "On a log2 scale, the breast cancer cell line data from 58 datasets showed that CDCA2 expression was significantly up-regulated by an estimated eight-fold." (PMID 29467944, 2018). "The upstream sequence of exon 14 of CDCA2 gene (ENST00000380665) was acquired in breast cancer cell line UACC893." (PMID 24533689, 2014). "The expression level of CDCA2 was up-regulated in breast cancer as well as in lung cancer." (PMID 32913466, 2020).
colorectal cancer (6 papers, 2019 to 2022). A primary or metastatic malignant neoplasm that affects the colon or rectum. "A recent study found that overexpression of CDCA2 may target CCND1 to promote colorectal cancer cell proliferation and tumorigenesis via activation of the PI3K/AKT pathway." (PMID 32716971, 2020). "For example, CDCA2 modulates cyclin D1 expression as a result of PI3K/AKT pathway activation; thus, promoting the development of colorectal carcinoma cells." (PMID 34082692, 2022). "Overexpressed CDCA2 promotes proliferation of colorectal cancer (CRC) cells by targeting upregulation of cyclin D1 (CCND1) through activation of the phosphoinositide 3-kinase (PI3K)/AKT pathway, while a specific PI3K inhibitor (LY294002) blocks the pro-proliferative effect of CDCA2 on CRC cells." (PMID 34660326, 2021).
hepatocellular carcinoma (6 papers, 2020 to 2024). A malignant tumor that arises from hepatocytes. "Correlations between CDCA2 mRNA expression and clinicopathological characteristics of hepatocellular carcinoma patients from the TCGA LIHC_pan_caner_atlas_2018 dataset." (PMID 35694386, 2022). "Correlations between CDCA2 protein expression and clinicopathological characteristics in paraffin-embedded hepatocellular carcinoma samples." (PMID 35694386, 2022). "Our study demonstrated a similar CDCA2 expression pattern in hepatocellular carcinoma." (PMID 32913466, 2020). "In conclusion, our findings suggested that CDCA2, CDCA3, CDCA4, CDCA5, and CDCA8 might have potential diagnostic and prognostic values for hepatocellular carcinoma." (PMID 32913466, 2020). "However, the role of CDCA2 in hepatocellular carcinoma remained unknown." (PMID 32913466, 2020). "However, the relationship between CDCA2 expression and the clinicopathological characteristics of hepatocellular carcinoma (HCC) is unknown." (PMID 35372372, 2021). "In conclusion, we supposed that CDCA2, CDCA3, CDCA4, CDCA5 and CDCA8 might be oncogenes in hepatocellular carcinoma." (PMID 32913466, 2020). "Although some researchers suggested that CDCAs might act as oncogenes in hepatocellular carcinoma as well; one of this family, CDCA2, was not revealed clearly so far." (PMID 32913466, 2020). "In Wurmbach's dataset 20, CDCA2, CDCA3, CDCA4, CDCA5 and CDCA8 were up-regulated in hepatocellular carcinoma (HCC), with fold changes of 1.813, 3.214, 1.832, 2.422 and 1.693, respectively." (PMID 32913466, 2020).
prostate carcinoma (5 papers, 2020 to 2023). A carcinoma that arises from epithelial cells of the prostate gland. "Our finding is consistent with a previous study related to prostate cancer, which indicates that CDCA2 is positively correlated with the histological grade, clinical stage, and prognosis." (PMID 34660326, 2021). "A serial experiments and dataset analysis further confirmed that CDCA2 was upregulated in primary patients' samples and positively correlated with the patients' clinical stage and poor progression in prostate cancer." (PMID 32509575, 2020). "CDCA2 is overexpressed in prostate cancer patients and regulates cell proliferation." (PMID 37733705, 2023). "In conclusion, our paper found that CDCA2 is overexpressed in prostate cancer patients." (PMID 32509575, 2020). "The IHC staining results showed that CDCA2 was overexpressed in the prostate cancer tissues." (PMID 32509575, 2020). "Our data suggest that CDCA2 might be a potential therapeutic biomarker for prostate cancer." (PMID 32509575, 2020). "It has been reported that upregulation of CDCA2 regulated by HIF-1α inhibited apoptosis and promoted proliferation in prostate cancer." (PMID 34545328, 2021). "Besides the direct regulation by HIF-1α and SMAD3, through some other public ChIP-Sequencing dataset, we also found that, in PCa, CDCA2 was a directly regulated by MEN1, which function as an oncogene in prostate cancer (GEO: GSE132827)." (PMID 32509575, 2020).
liver cancer (4 papers, 2022 to 2025). An epithelial or non-epithelial malignant neoplasm that arises from the liver. "Overexpression of CDCA2 has been reported in colorectal, prostate, and liver cancer, among others, and it was reported to be positively correlated to the disease stage." (PMID 40565058, 2025). "The involvement of CDCA2 in cancer was first suggested in 2010, when elevated CDCA2 expression was preliminarily observed in 4 cases of liver cancer tissues." (PMID 35694386, 2022).
lung carcinoma (4 papers, 2020 to 2021). "We found CDCA2 was increased in PCaPC3 cells (GSE53012 and GSE80657) or lung cancer A549 cells (GSE48134) in the hypoxia condition." (PMID 32509575, 2020).
colon cancer (3 papers, 2020 to 2025). "Among the 14 model genes, the expression levels of FZD3, CDC25C, CDCA2, NEBL, and HMMR were positively correlated with better prognosis of colon cancer." (PMID 41425852, 2025).
oral cancer (3 papers, 2013 to 2022). "For example, a marked augmentation of CDCA2 is a common event for oral cancer, and its overexpression blocked G1 arrest by suppressing cyclin-dependent kinase inhibitors and triggering apoptosis." (PMID 36588796, 2022). "We observed CDCA2 overexpression in most oral cancer specimens, and its nuclear accumulation increased with tumoral progression and advanced-tumor stage." (PMID 23418564, 2013).
gastric adenocarcinoma (2 papers, 2022 to 2025). "Interestingly, CDCA2 not only enhances the proliferation of CRC cells by activating the AKT/CCND1 pathway but also reduces the radiosensitivity of gastric adenocarcinoma by activating the PI3K/AKT pathway." (PMID 40565588, 2025). "Notably, the inhibition of CDCA2 and CDCA5 activities in lung and gastric adenocarcinoma, respectively, resulted in the downregulation of CCNE1 expression, thereby inhibiting cancer cell proliferation and blocking it in the G1 phase." (PMID 36004205, 2022).
squamous cell carcinoma (2 papers, 2013 to 2018). A carcinoma arising from squamous epithelial cells. "CDCA2 is required in the formation of mitotic chromatin and is involved in the progression of human squamous cell carcinoma." (PMID 29642861, 2018).
astrocytoma (1 paper, 2023). "CDCA2 upregulation was observed to be associated with shorter overall survival in a subgroup stratified analysis of IDH status (Mut), WHO grade (G3), histological type (astrocytoma and oligodendroglioma), and primary therapy outcome (PD and SD)." (PMID 37733705, 2023).
clear cell renal cell carcinoma (1 paper, 2021). "Recently, more studies have focused on the role of CDCA2 in tumorigenesis development; for instance, CDCA2 was shown to be upregulated in clear cell renal cell carcinoma tissues, and the magnitude of upregulation correlated with the degree of malignancy." (PMID 34660326, 2021).
COVID-19 (1 paper, 2022). A disease caused by infection with severe acute respiratory syndrome coronavirus 2. "In the COVID-19 dataset, TYMS(AUC:0.952), RRM2(AUC:0.954), CDCA2(AUC:0.946) and TOP2A(AUC:0.958) exhibited good diagnostic efficiency for differentiating the patients with SARS-CoV-2 from healthy controls." (PMID 35958619, 2022). "For the remaining five hub genes (TYMS, CDCA2, TOP2A, RRM2 and IFI44), there are no studies reporting their role in COVID-19 or pSS, which emphasizes its importance in future research." (PMID 35958619, 2022).
endometrial carcinoma (1 paper, 2020). A malignant tumor arising from the epithelium that lines the cavity of the uterine body. "When it comes to uterine mixed endometrial carcinoma, another distinctive pattern emerged and the most were the high mRNA expression of almost all CDCA members except CDCA3/7, and the missense mutation of NUF2, CDCA2/3/5, CBX2, CDCA7/8." (PMID 32913454, 2020).
gastric intestinal type adenocarcinoma (1 paper, 2022). An adenocarcinoma of the stomach arising on a background of intestinal metaplasia. "Additionally, CDCA2 transcriptional levels were significantly elevated in gastric mixed adenocarcinoma and gastric intestinal-type adenocarcinoma, for which the fold changes were 3.287 and 3.851, respectively." (PMID 34082692, 2022).
uterine endometrioid carcinoma (1 paper, 2020). "In uterine endometrioid carcinoma, the prevalent high mRNA expression of almost all CDCAs except CDCA7, the amplification of NUF2, CDCA3/5, the deep deletion of CDCA2 and the missense mutation of CDCA7 presented the most common altered genetic events." (PMID 32913454, 2020).
uterine papillary serous carcinoma (1 paper, 2020). "As to uterine serous carcinoma/uterine papillary serous carcinoma, the most common alterations were the high mRNA expression of all CDCA members, the amplification of CDCA5, CBX2 and CDCA8 and the missense mutation of CDCA2/7." (PMID 32913454, 2020).